ACSL4 (acyl-CoA synthetase long chain family member 4)
Diseases named in the same sentence as ACSL4 in open-access papers (continued):
Sharing a sentence is not in itself a finding about the gene and the disease.
cancer (continued). "Extensive research has emphasized the clinical significance of ACSL4 across diverse cancers, serving dual roles as a predictive and prognostic biomarker." (PMID 38562143, 2024). "Collectively, these results indicate that RTKs promote ferroptosis by upregulating c-Myc mediated expression of ACSL4 in cancer cells." (PMID 39604370, 2024). "Recent studies have shown that ACSL4 is abnormally expressed in many types of cancer and is related to poor patient survival." (PMID 38548749, 2024). "Compared to normal tissues, ACSL4 is downregulated in breast cancer, bladder cancer, and lung cancer, suggesting that these cancer cells regulate lipid metabolism to inhibit ferroptosis." (PMID 39769177, 2024). "Taken together, the distinctive involvement of ACSL4 in ferroptosis, coupled with its relevance to cancer, positions it as a prospective target for therapeutic interventions." (PMID 38562143, 2024). "This study provides a novel approach to enhance cancer‐immunogenic ferroptosis by boosting ROS generation, AA delivery, and IFN‐γ promoted ACSL4 expression, which holds great promise for cancer treatment." (PMID 39352071, 2024). "ACSL4 is elevated in BC tissues compared with in healthy tissues adjacent to the cancer, and ACSL4 expression is negatively correlated with ER." (PMID 38528461, 2024). "Here we show that oncogenic activation of RTKs/RAS/RAF signaling pathway promotes cancer cell ferroptosis via c-Myc mediated upregulation of ACSL4." (PMID 39604370, 2024). "Overall, our study provides important insights into ACSL4 activity regulation and its potential role in cancer therapy." (PMID 38720107, 2024). "Inhibitors of FSP1 and inhibition of ACSL4 (e.g., through a high-fat diet) can increase and decrease the sensitivity of cancer cells to ferroptosis, respectively." (PMID 39090114, 2024). "We further showed that RTKs/RAS/RAF promote ferroptosis by upregulating c-Myc mediated expression of ACSL4 in cancer cells." (PMID 39604370, 2024). "Ionizing Radiation (IR) induces elevated ROS and ACSL4 expression in cancer cells, promoting ferroptosis." (PMID 39845670, 2024). "Overexpression of ACSL4 in cancer cells resistant to ferroptosis, such as LNCap and K562, significantly increases their sensitivity to this process." (PMID 39769177, 2024). "This discovery aligns with previous research on the regulatory role of ACSL4 in other cancer types but, for the first time, highlights the central role of ACSL4 in HBV‐HCC." (PMID 39268355, 2024). "At the beginning of this study, we analyzed the expression of ACSL4 in pan-cancer and the results showed that ACSL4 was differential expression gene in most cancers, including CHOL." (PMID 37193981, 2023). "ACSL4 is a key enzyme for fatty acid oxidation and reshapes the lipid spectrum in cancer cells under the action of arachidonic acid (AA), increasing lipid peroxidation levels and ferroptosis." (PMID 38288118, 2023). "Conversely, targeting ACSL4-dependent ferroptosis effectively kills cancer cells, especially apoptosis-evading cells." (PMID 37372148, 2023). "According to previous studies, ACSL4 promotes ferroptosis sensitivity by synthesizing PUFA, and pharmacological inhibiting of ACSL4 with thiazolidinediones has been shown to prevent cancer tissue demise in a murine model of ferroptosis." (PMID 37923740, 2023). "Acyl-CoA synthetase long chain family member 4 (ACSL4) is critical for apoptosis in iron chain cancer cells." (PMID 37168653, 2023). "Analyses of previously published E2F1 ChIP-Seq data sets revealed strong E2F1 protein occupancy at several putative E2F binding motifs at the ACSL4 promoter in various cancer cell lines." (PMID 37183818, 2023).
cancer (continued). "In support of emerging regulatory roles of metabolism in various forms of cancer, we identified the acyl-CoA synthetase long-chain family member (ACSL4) as a direct miR-211 target." (PMID 38115140, 2023). "Functionally, ACSL4 performs different roles in regulating ferroptosis, making it a potential target for cancer therapy." (PMID 37372148, 2023). "Activating the Hippo pathway can suppress downstream YAP, leading cancer cells resistant to ferroptosis by downregulating acyl-CoA synthetase long-chain family member 4 (ACSL4) and TCP friendly rate control (TFRC)." (PMID 38239395, 2023). "verified that IFN-γ treatment induces cancer cell ferroptosis through the STAT1/IRF1/ACSL4 axis in hepatocellular carcinoma." (PMID 38288118, 2023). "For instance, fatty-acid β-oxidation enhances STAT3 acetylation, upregulating ACSL4-dependent phospholipid biosynthesis, which in turn enhances mitochondrial membrane potential and protects cancer cells from apoptosis induction." (PMID 37372148, 2023). "ACSL4 expression had a correlation with immune cells including CD4 + T cells, neutrophils, cancer associated fibroblasts (CAFs), macrophages and common lymphoid progenitors." (PMID 37193981, 2023). "A recent review summarizes expression of ACSL4 in various cancers and its potential role as a target and biomarker." (PMID 37306503, 2023). "Through ACSL4 and probably other as yet unidentified pathways and targets, miR-211 appears to maintain lipidomic and metabolic homeostasis and protect against the cancer cell adaptations that promote proliferation, migration, and resistance to cell death." (PMID 38115140, 2023). "ACSL4-dependent ferroptosis has been considered an effective treatment for apoptosis-resistant cancers." (PMID 37372148, 2023). "ACSL4 has been demonstrated to play a pivotal role in both normal physiology as well as in a variety of disease states, including breast and other cancers." (PMID 37306503, 2023). "The fatty acid-activating enzyme, ACSL4, has been demonstrated to play a role in the malignant phenotype of a variety of cancers, including breast." (PMID 37306503, 2023). "In fact, a number of studies have demonstrated that ACSL4 expression is regulated by a variety of miRNA species in several cancers, including hepatocellular, colorectal and ovarian." (PMID 37306503, 2023). "The increased expression and activity of ACSL4 have been observed in many cancer types and it is well-known biomarkers of ferroptosis." (PMID 38078907, 2023). "ACSL4 expression directly correlates with sensitivity of cancer cells to ferroptosis; deletion of ACSL4 suppresses ferroptosis sensitivity, while overexpression sensitizes cells to ferroptosis." (PMID 35065965, 2022). "In the present review, we provide an update on understanding the controversial roles of ACSL4 in different cancer cells." (PMID 35910359, 2022). "To evaluate ACSL4 mRNA expression patterns in different cancers, we analyzed ACSL4 expression between normal tissues and tumors using Oncomine database." (PMID 35126480, 2022). "The dysregulation of ACSL3 and ACSL4, which belong to the long-chain fatty acyl CoA synthetase family (ACSLs), affects the behavior of various cancer cells." (PMID 36497375, 2022). "Instead, we find that ACSL4-dependent processes have an unanticipated cancer-promoting effect during HCC formation, which is most likely due to aggravated liver damage as demonstrated by increased hepatic fibrosis." (PMID 35963845, 2022). "A previous study has shown that ACSL4, a positive activator of ferroptosis, is overexpressed in multiple cancer types." (PMID 36528763, 2022). "A study has shown that the PKCβII (one of PKCs isoforms)–ACSL4 pathway modulated ferroptosis and anti-cancer immunity." (PMID 36497375, 2022). "We explored the potential relationship between genetic changes in ACSL4 and clinical outcomes in patients with different types of cancer." (PMID 35126480, 2022).
cancer (continued). "In this article, we introduce the cell localization, structure and function of ACSL4, and mainly summarize the evidences of ACSL4 as a potential biomarker and therapeutic target in many cancer types." (PMID 35910359, 2022). "ACSL4 activates PUFAs and sensitizes cancer cells to ferroptosis in immunotherapy-relevant settings." (PMID 35910359, 2022). "We aim to analyze the expression and prognostic value of ACSL4 in pan-cancer, and further explore the correlation between ACSL4 and immune infiltration." (PMID 35126480, 2022). "In fact, the predictive value of ACSL4 in several cancers has been revealed by a multiple databases analysis." (PMID 35910359, 2022). "CNV analysis showed that ACSL4 CNV was positively correlated with ACSL4 expression in 10 cancers, which was consistent with cBioPortal results." (PMID 35126480, 2022). "RNA‐seq data from our study showed decreased expression of ACSL1, ACSL3 and ACSL4 in NAT10‐depleted cancer cells, which further confirmed that the mRNA transcripts of these genes are controlled by NAT10‐dependent ac4C mRNA acetylation." (PMID 36149760, 2022). "Using the cBioPortal database, we explored the genetic changes of ACSL4 in various cancers and their correlation with patients’ OS and PFS in TCGA-Pan cancer panel." (PMID 35126480, 2022). "A study has reported that ACSL4 is required for ferroptotic cancer cell death via mediating production of 5-HETE (5-hydroxyeicosatetraenoic acid)." (PMID 35456964, 2022). "By assembling the Cancer Cell Line Encyclopedia (CCLE), we further analyzed the expression of ACSL4 in cancer cell lines." (PMID 35126480, 2022). "Patients with ACSL4 hypermethylation had poorer prognosis and survival in other cancers: ACC, HNSC, KIRC, LUSC, PAAD and UCS." (PMID 35126480, 2022). "Cancer patients expressing a high level of ACSL4 who are treated with ICB therapy present higher overall survival and progression-free survival." (PMID 35847022, 2022). "Studies showed that ionizing radiation induced ferroptosis in cancer cells by inducing ROS and activating ACSL4." (PMID 35910359, 2022). "The results suggest that ACSL4 can affect the prognosis of cancer patients through its interaction with invasive immune cells." (PMID 35126480, 2022). "Here, we report the discovery of a photosensitizer, namely TPCI, which can evoke ACSL4-independent ferroptosis of cancer cells in photodynamic therapy." (PMID 36517470, 2022). "Understanding the exact role of ACSL4 in cancer and the molecular mechanism involved would provide ideas for finding new targets for cancer diagnosis and treatment and developing new strategies for therapy." (PMID 35910359, 2022). "In this study, we analyzed the expression pattern and prognostic value of ACSL4 in various cancers using data from multiple public databases and discovered the impact of genetic changes of ACSL4 on prognosis." (PMID 35126480, 2022). "Here, we present a summary of the current knowledge on ACSL3 and ACSL4 and their functions in various cancers." (PMID 36497375, 2022). "Accordingly, ACSL4 transcript levels were found to be downregulated in ferroptosis-resistant cancer cell lines." (PMID 35065965, 2022). "Compared with ACSL4 wild type, ACSL4 mutation caused significant changes in CD4+ T cells, DC, macrophages and CAF, and showed opposite trends in both types of cancer." (PMID 35126480, 2022). "This study analyzed the expression of ACSL4 in generalized carcinoma, and for the first time analyzed the genetic and epigenetic changes of ACSL4 in different cancers, as well as its impact on survival and prognosis." (PMID 35126480, 2022). "An ACSL4-independent ferroptosis is urgent needed to directly benefit the suppression of most cancer cells regardless their ACSL4 expression levels." (PMID 36517470, 2022). "Then, analysis of Acsl4 expression in public databases such as The Cancer Gene Atlas (TCGA) and Rembrandt revealed its relatively low expression in GBM compared with LGG." (PMID 35697672, 2022).
cancer (continued). "Through ONCOMINE, TIMER (Tumor Immune Estimation Resource), GEPIA (Gene expression Profiling Interactive), UALCAN and HPA, ACSL4 expression patterns of in pan-cancer were analyzed." (PMID 35126480, 2022). "The relationship between ACSL4 expression and prognosis in patients with various cancers was analyzed using the PrognoScan database." (PMID 35126480, 2022). "In this study, the expression and prognostic value of ACSL4 in different cancers were analyzed using multiple online public databases." (PMID 35126480, 2022). "Increased ACSL4 expression synergizes with arachidonic acid (AA) treatment to trigger potent ferroptosis in various cancer cell lines in an ACSL4-dependent manner." (PMID 35847985, 2022). "Below, we would like to introduce the relationship between ACSL4 and different cancers, respectively." (PMID 35910359, 2022). "ACSL4 is expressed differently in several cancers and has emerged as an attractive therapeutic target because its inhibition reduces cancer cell invasion and migration." (PMID 36497375, 2022). "The results showed that certain genes (such as GPX4, SLC7A11 and GSS) displayed higher expression, while others (such as ACSL1 and ACSL4) displayed lower expression in some cancer types." (PMID 34975326, 2022). "More and more evidence highlights the important role of ACSL4 in regulating the proliferation and apoptosis of cancer cells." (PMID 35126480, 2022). "The 30 patients from our Cancer Center were divided into high- and low-ACSL4-expression groups (15 samples each) for IHC analysis." (PMID 34868963, 2021). "Recently, ferroptosis has also been proven to be interrelated with cancer radiotherapy, which induces ACSL4 expression and enhances oxidative damage in a variety of cancers, including NSCLC, melanoma and esophageal cancer." (PMID 35118067, 2021). "Nevertheless, the precise role of ACSL4 in cancer still needs to be carefully investigated in future studies." (PMID 34053456, 2021). "Results indicated that the four hub genes were all significantly related to metastasis (P < .05); AKAP9, VPS13C, and ACSL4 were positively associated with metastatic ability, while HMOX2 was negatively associated with cancer metastasis." (PMID 33663112, 2021). "We firstly assessed ACSL4 expression among 33 different types of cancers using the TCGA database, and several cancers demonstrated statistically significant differences in the ACSL4 expression level when compared with the corresponding normal control samples." (PMID 34053456, 2021). "Immunohistochemistry was used to detect CD8+ T cell infiltration in tumors with high and low ACSL4 expression obtained from patients at the Fudan University Shanghai Cancer Center." (PMID 34868963, 2021). "ACSL4 expression level has been studied in most cancer types, and ACSL4 becomes a promising drug target for certain cancers." (PMID 34053456, 2021). "Accumulating evidence has highlighted the vital role of ACSL4 in regulating cancer cell proliferation and apoptosis." (PMID 32357142, 2020). "So far, it has been reported that the ACSL4 dysregulation is related to a great number of malignant tumors such as, breast cancer, colon adenocarcinoma and gastric cancer." (PMID 32350243, 2020). "ACSL4 has been previously reported overexpressed in malignant tumors, and together with ACSL1 and SCD form a metabolic axis involved in CRC progression." (PMID 31339921, 2019). "ACSL3 and ACSL4 expression levels have been reported to be frequently altered in cancer but here we provide evidence that they have also an altered expression profile in senescence induced by oncogenic H-Ras." (PMID 30413053, 2018). "The analysis of ACSL4 gene expression in cancer from Oncomine was in accordance with the survival analysis from PrognoScan." (PMID 27171439, 2016).
cancer (continued). "The cancer pathway finder PCR array revealed 9 genes, including ACSL4, BIRC3,CA9, CCL2, FLT1, FOXC2, G6PD, IGFBP3 and SNAI2, with significantly altered expression in the siRNA-treated MCF-7 cells." (PMID 27478411, 2016). "When ACSL4 was expressed, analyses showed cancer to be the disease with the lowest p-value among diseases and disorders." (PMID 26536660, 2015). "Among the PCa patients with high stage (Stage III) PCa, ACSL4 expression percentage scores were significantly higher than those with a low stage (Stage I or II) cancer (p = 0.04)." (PMID 26636648, 2015). "Enriched canonical pathways were also analyzed through IPA, which interestingly revealed p70S6K, mTOR and the signaling of molecular mechanisms of cancer to be among the top canonical pathways triggered by ACSL4 with the lowest p-values." (PMID 26536660, 2015). "This specificity should increase the therapeutic index of combination-based therapies for ACSL4-overexpressing cancers." (PMID 22808264, 2012). "Conversely, ACSL4 and PUFAs augment metastasis in cancer cells." (PMID 41596341, 2026). "This contrasts with the upregulated expression of ACSL1 and ACSL4 in these cancers." (PMID 40932861, 2025). "Clinically, ACSL4 has improved the survival rate of cancer patients treated with ICIs." (PMID 41293165, 2025). "In summary, ACSL4 can promote ferroptosis in cancer cells through the esterification of AA and AdA." (PMID 40932861, 2025). "Recent studies have highlighted the role of ACSL4 in ferroptosis within cancer cells, suggesting that ACSL4 may promote cell proliferation and invasion, while also sensitizing cancer cells to ferroptosis." (PMID 41288931, 2025). "Given the high expression of ACSL4 in various cancers, the specific activation of ferroptosis may represent an ideal anti-cancer strategy." (PMID 40932861, 2025). "Inhibition of ACSL4 has been shown to enhance chemotherapy efficacy in cancer cells." (PMID 41288931, 2025). "Furthermore, ACSL4/GPX4/PHLDA2 triple-knockout cancer cell lines were resistant to ferroptosis, indicating that the mechanism is independent of GPX4." (PMID 39188677, 2024). "Downregulation of ACSL4 suppressed ferroptosis in several cancer cells." (PMID 38292937, 2024). "Hence, ACSL4-dependent processes have an unanticipated cancer-promoting effect on HCC tumorigenesis." (PMID 38993573, 2024). "These metabolites or extracts trigger ferroptosis mainly by targeting ACSL4 in the lipid metabolism pathway, which may improve the therapeutic effects on cancer when combined with chemotherapy or targeted therapy." (PMID 38292937, 2024). "The cancer genome atlas database shows low expression of ACSL4 in PCa." (PMID 39465761, 2024). "In cancer cells, the labile iron pool and increase in lipid content and ACSL4 expression may lead to a GPX4-dependent increase, resulting in vulnerability to GPX4 inhibitors." (PMID 39174525, 2024). "Furthermore, we observed frequent crosstalk between ACSL4+CAFs and cancer cells, consistent with previous research indicating that CAFs promote cancer cell proliferation and invasion." (PMID 39238647, 2024). "Prior research has identified ACSL4 as an oncogene in various cancers, including HCC." (PMID 39563427, 2024). "Further, ACSL4 (acyl-CoA synthetase long chain family member 4) dictates sensitivity to ferroptosis and, usually, its expression is upregulated in some types of cancer rather than in healthy cells, determining a potential selectivity for cancer cells." (PMID 37132605, 2024). "In addition, FSP1 and ACSL4 are critical regulators of ferroptosis, with significant implications for cancer therapy." (PMID 39090114, 2024). "Moreover, CD8+ T cell-derived IFN-γ and arachidonic acid from the TME induce cancer cell ferroptosis by stimulating ACSL4 expression." (PMID 39614322, 2024).